UBB (ubiquitin B)
Description:
[Ubiquitin]: Exists either covalently attached to another protein, or free (unanchored). When covalently bound, it is conjugated to target proteins via an isopeptide bond either as a monomer (monoubiquitin), a polymer linked via different Lys residues of the ubiquitin (polyubiquitin chains) or a linear polymer linked via the initiator Met of the ubiquitin (linear polyubiquitin chains). Polyubiquitin chains, when attached to a target protein, have different functions depending on the Lys residue of the ubiquitin that is linked: Lys-6-linked may be involved in DNA repair; Lys-11-linked is involved in ERAD (endoplasmic reticulum-associated degradation) and in cell-cycle regulation; Lys-29-linked is involved in proteotoxic stress response and cell cycle; Lys-33-linked is involved in kinase modification; Lys-48-linked is involved in protein degradation via the proteasome; Lys-63-linked is involved in endocytosis, DNA-damage responses as well as in signaling processes leading to activation of the transcription factor NF-kappa-B. Linear polymer chains formed via attachment by the initiator Met lead to cell signaling. Ubiquitin is usually conjugated to Lys residues of target proteins, however, in rare cases, conjugation to Cys or Ser residues has been observed. When polyubiquitin is free (unanchored-polyubiquitin), it also has distinct roles, such as in activation of protein kinases, and in signaling.
Synonyms: MGC8385; FLJ25987; HEL-S-50
Tractability: Small molecule: a structure with a bound ligand is known. Antibody: UniProt places it where antibodies can reach, with high confidence; its Gene Ontology location is reachable by antibodies, with high confidence. PROTAC: UniProt records ubiquitination sites on it; ubiquitination databases record sites on it.
Gene: Protein-coding gene on chromosome 17 (16,380,667 to 16,382,745, forward strand). Ensembl gene ENSG00000170315.
Subcellular location: Cytoplasm (Ubiquitin); Nucleus; Mitochondrion outer membrane
Subcellular location (Human Protein Atlas): Cytosol; Acrosome; Equatorial segment
Pathways (Reactome):
Immune System: AMPK-induced ERAD and lysosome mediated degradation of PD-L1(CD274); Activation of IRF3, IRF7 mediated by TBK1, IKKε (IKBKE); Activation of NF-kappaB in B cells; Alpha-protein kinase 1 signaling pathway; Antigen processing: Ubiquitination & Proteasome degradation; CLEC7A (Dectin-1) signaling; DDX58/IFIH1-mediated induction of interferon-alpha/beta; Dectin-1 mediated noncanonical NF-kB signaling; Downstream TCR signaling; ER-Phagosome pathway; FCERI mediated NF-kB activation; GSK3B-mediated proteasomal degradation of PD-L1(CD274); IKK complex recruitment mediated by RIP1; IRAK1 recruits IKK complex; IRAK1 recruits IKK complex upon TLR7/8 or 9 stimulation; IRAK2 mediated activation of TAK1 complex; IRAK2 mediated activation of TAK1 complex upon TLR7/8 or 9 stimulation; ISG15 antiviral mechanism; Inactivation of CSF3 (G-CSF) signaling; Interferon alpha/beta signaling; Interleukin-1 signaling; JNK (c-Jun kinases) phosphorylation and activation mediated by activated human TAK1; MAP3K8 (TPL2)-dependent MAPK1/3 activation; NIK-->noncanonical NF-kB signaling; NOD1/2 Signaling Pathway; Negative regulation of FLT3; Negative regulators of DDX58/IFIH1 signaling; PD-L1(CD274) glycosylation and translocation to plasma membrane; Regulation of NF-kappa B signaling; Regulation of TBK1, IKKε (IKBKE)-mediated activation of IRF3, IRF7; Regulation of TBK1, IKKε-mediated activation of IRF3, IRF7 upon TLR3 ligation; Regulation of innate immune responses to cytosolic DNA; Regulation of signaling by CBL; SPOP-mediated proteasomal degradation of PD-L1(CD274); Signaling by CSF1 (M-CSF) in myeloid cells; TAK1-dependent IKK and NF-kappa-B activation; TICAM1, RIP1-mediated IKK complex recruitment; TICAM1,TRAF6-dependent induction of TAK1 complex; TICAM1-dependent activation of IRF3/IRF7; TNFR2 non-canonical NF-kB pathway
and 164 more pathways
Gene Ontology:
Molecular function: protein binding; protein tag activity; pyridoxal phosphate binding
Biological process: mitochondrion transport along microtubule; neuron projection morphogenesis; positive regulation of protein monoubiquitination; positive regulation of protein ubiquitination; regulation of mitochondrial membrane potential; regulation of neuron apoptotic process; regulation of proteasomal protein catabolic process; modification-dependent protein catabolic process; protein homotetramerization; protein ubiquitination
Cellular component: extracellular exosome; extracellular region; mitochondrial outer membrane; mitochondrion; neuron projection; neuronal cell body; nucleus; vesicle; cytosol; cytosolic ribosome; endocytic vesicle membrane; endoplasmic reticulum membrane; endosome membrane; nucleoplasm; plasma membrane; cytoplasm
Genetic constraint (gnomAD): Loss-of-function variants: 11 observed, 12.05 expected, observed/expected ratio (o/e) 0.91, 90% interval 0.57 to 1.5. The synonymous counts are far from expectation, so gnomAD's model fits this gene poorly and the ratio says little. Missense variants: 76 observed, 290.96 expected, observed/expected ratio (o/e) 0.26, 90% interval 0.22 to 0.32. Synonymous variants: 168 observed, 114.85 expected, observed/expected ratio (o/e) 1.46, 90% interval 1.29 to 1.66.
Homologues: Orthologues: guinea pig UBB (100% identical), macaque UBB (100% identical), pig UBB (100% identical), dog UBB (99% identical), mouse Ubb (99% identical), rat Ubb (99% identical), zebrafish UBB (99% identical), Drosophila melanogaster CG11700 (88% identical). Paralogues in human: UBC (99% identical), ZFAND4 (10% identical), ANKUB1 (7% identical), UBA52 (6% identical), RPS27A (5% identical), UBD (3% identical), ISG15 (2% identical), UBL4A (2% identical), UBL4B (2% identical), NEDD8 (1% identical).
Diseases named in the same sentence as UBB in open-access papers:
UBB is named in the same sentence as 61 diseases in open-access papers, as found by Europe PMC text mining. Sharing a sentence is not in itself a finding about the gene and the disease. The quoted sentences say what the papers report.
Alzheimer disease (19 papers, 2009 to 2025). A progressive, neurodegenerative disease characterized by loss of function and death of nerve cells in several areas of the brain leading to loss of cognitive function such as memory and language. "Intensification of this molecular misreading and an accumulation of UBB+1 in multiple areas of the brain is a hallmark of neurodegeneration, including that associated with Alzheimer’s disease." (PMID 33842548, 2021). "UBB frame shifting mutation (UBB+1) impedes proteasomal proteolysis, and has been extensively identified in Alzheimer disease (AD), FTD and Huntington disease (HD) as pathological hallmark." (PMID 28282387, 2017). "Moreover, mutations in UBB have been associated with the formation of neurofibrillary tangles in Alzheimer’s disease." (PMID 38002524, 2023). "Interestingly, Vms1 overexpression in yeast has been shown to counteract the mitochondrial damage and cell death induced by the expression of UBB+1, a frame-shift variant of ubiquitin B, which is associated with Alzheimer’s disease." (PMID 26287188, 2015). "It has been shown that GAGAG motifs in RNA are hot spots for a dinucleotide deletion (ΔGA) that leads to + 1 reading frame shift of amyloid precursor protein and ubiquitin-B in Alzheimer’s disease (AD) and Down syndrome." (PMID 37740734, 2023). "The link between UBB+1 and Alzheimer’s disease (AD) is the most extensively studied and is the subject of several reviews." (PMID 33842548, 2021). "Accumulation of ubiquitin B (UBB+1), a frame-shift, truncated form of ubiquitin leads to neuronal cell death and is a hallmark of Alzheimer disease." (PMID 32961852, 2020). "To elucidate causative effects and neuropathological consequences of UBB+1 accumulation, we used a UBB+1 expressing transgenic mouse line that models UPS inhibition in neurons and exhibits behavioral phenotypes reminiscent of Alzheimer’s disease (AD)." (PMID 22730000, 2012).
ovarian carcinoma (9 papers, 2011 to 2023). A malignant neoplasm originating from the surface ovarian epithelium. "Inhibited UBB expression was associated with poorer survival outcomes in ovarian cancer." (PMID 36983585, 2023). "The expression of UBB is significantly suppressed in certain cancers, including endometrial carcinoma and ovarian cancer." (PMID 37124501, 2023). "The results of Kaplan-Meier survival analysis illustrated that lower UBB expression predicted poor progression-free-survival and overall survival both in ovarian cancers and cisplatin treated ovarian cancers, respectively." (PMID 33892654, 2021). "The ubiquitin-encoding gene UBB is involved in several cancers, and suppression of UBB transcription plays a role specifically in ovarian carcinoma-specific changes." (PMID 31257224, 2019). "Prominently, the gene encoding ubiquitin B (UBB) shows a high correlation between methylation and expression in both data sets and RAB25 a known ovarian cancer suspect is also found in the TCGA data set." (PMID 22174824, 2011). "This study may advance the understanding of the mechanism of cisplatin resistance in ovarian cancer and suggest that miR-454 and UBB may be two novel biomarker and therapeutic targets for ovarian cancer patients." (PMID 33892654, 2021). "UBB is strongly suppressed in some cancers, including endometrial carcinoma and ovarian cancer." (PMID 33134373, 2020). "We also found that apoptosis-related genes, URI1, PAK2, PARP1, CLU and TIMP3, were highly expressed, while immune-related genes, UBB, RPL11, CAV1, NUPR1 and Hsp90ab1, were lowly expressed in ovarian cancer cells." (PMID 37124501, 2023). "RT-qPCR analysis revealed that URI1, PAK2, PARP1, CLU, and TIMP3 were significantly upregulated, while UBB, RPL11, CAV1, NUPR1, and Hsp90ab1 were significantly downregulated in the ovarian cancer samples." (PMID 37124501, 2023).
breast carcinoma (8 papers, 2009 to 2023). "Two new control genes for breast cancer – UBB and RPS11 – have been identified and validated by RT-QPCR." (PMID 19187545, 2009). "We used primers for the gene sequences of UBB, ESR1 (for luminal or ER/PR+ cancer cells), HER2 and GRB7 (for HER2+ cancer cells), EPCAM, KRT7, KRT8, KRT18, and KRT19, all of which have been commonly discussed for the purpose of breast cancer diagnosis." (PMID 28936247, 2015). "Of note, this does not exclude the possibility that other genes including UBB (Ubiquitin B), PSMC6 (Proteasome 26S subunit, ATPase 6), PEN1 (Penetration 1), HIST1H2BB (Histone Cluster 1 H2B Family Member B) would also play a role in the development of breast cancer." (PMID 34386417, 2021).
tauopathies (5 papers, 2012 to 2022). "In tauopathies and polyglutamine diseases, a mutant form of ubiquitin B (UBB+1) accumulates in disease-specific aggregates." (PMID 22730000, 2012). "Line 3413 may also be predictive for other conformational diseases, including related tauopathies and polyglutamine diseases, in which UBB+1 accumulates in their cellular hallmarks." (PMID 25852488, 2015). "Interestingly, a frame-shift mutant of ubiquitin B (UBB+1) has been found to accumulate in the dystrophic neurites and neurofibrillary tangles of AD as well as other tauopathies and in polyglutamine diseases but not in synucleinopathies." (PMID 25031631, 2014).
Huntington disease (4 papers, 2017 to 2023). Huntington disease (HD) is a rare neurodegenerative disorder of the central nervous system characterized by unwanted choreatic movements, behavioral and psychiatric disturbances and dementia. "Because neurodegenerative diseases, including AD and Huntington’s disease, are age-related disorders, we evaluated the effect of UBB+1 on chronologically aged cells and we found that low UBB+1 expression could extend yeast life span." (PMID 29950972, 2018).
cervical cancer (3 papers, 2013 to 2021). A primary or metastatic malignant neoplasm involving the cervix. "We also assessed the cancer stem cell frequency, tumorsphere formation, and in vivo growth of human cervical cancer xenografts after UbB silencing." (PMID 24367661, 2013). "Our results demonstrate that UbB was significantly increased in prolonged Trichostatin A-selected HeLa cells and it played a key role in the maintenance of cervical cancer stem-like cells." (PMID 24367661, 2013). "The expression of UbB shows a significant increase in cervical cancer following chemotherapy compared with non- chemotherapy (p=0.0059, two-way ANOVA test)." (PMID 24367661, 2013). "Over expression of ubiquitin B (UBB) was reported in non-small cell lung cancer and cervical cancer, UBB may serve as a potential therapy and prevention target." (PMID 31844595, 2019). "Clinical characteristics and UbB gene expression in cervical cancer ascites." (PMID 24367661, 2013). "We hypothesized that UbB plays a critical role in the function of cervical cancer stem cells." (PMID 24367661, 2013). "We found that the relative expression of UbB in cervical cancer without chemotherapy ranged from 0.85 to 6.05, compared to adjacent tissues, while cervical cancer tissue following chemotherapy exhibited a UbB expression from 3.19 to 34.69." (PMID 24367661, 2013).
female infertility (3 papers, 2020 to 2024). Diminished or absent ability of a female to achieve conception. "The targeted destruction of the polyubiquitin gene UBB leads to male and female infertility in mice, and germ cells are blocked during meiotic prophase I." (PMID 36766254, 2023). "The disruption of UBB leads to male and female infertility resulting from the arrest of germ cells at meiosis prophase 1." (PMID 32218174, 2020).
Infertility (3 papers, 2020 to 2022). "However, it is still unclear how decreased Ub levels due to UBB deficiency result in infertility." (PMID 32218174, 2020). "Disruption in the UBB gene in both male and female mice resulted in infertile animals." (PMID 35774501, 2022).
lung carcinoma (3 papers, 2015 to 2024). "Whether other mechanisms are involved in the enhancement of radiosensitivity of UBB and UBC gene in lung cancer cells also warrants further investigation." (PMID 25820571, 2015).
major depression (3 papers, 2011 to 2019). "As UBB+1-ir cells were shown in both the DR and LC of 3413 tg mice, it is possible that UBB+1 accumulation is associated with depression in AD." (PMID 25852488, 2015). "These genes included SBNO2, CEACAM5, AKAP1, UBC, ACTB, UBB, and FOS for schizophrenia; SEC24C, PGLYRP1, ARHGAP4, RPL22, SLC6A11, and SYK for bipolar disorder; and SRRT, PARK2, LILRA4, STK17A, IGFBP2, and NF1 for major depression." (PMID 22373040, 2011).
neuroblastoma (3 papers, 2018 to 2024). Neuroblastoma (NB) is the most common solid, extracranial childhood tumor. "For instance, UBB silencing has been shown to significantly decrease the proliferation rate of neuroblastoma, hepatocarcinoma, breast, and PC cells." (PMID 38473264, 2024). "Indeed, UBB silencing in neuroblastoma, hepatocarcinoma, breast and prostate cancer cells significantly decreased the proliferation rate of all lines tested." (PMID 32751694, 2020). "It has been previously shown that overexpression of UBB+1 reduces the activity of the UPS in HeLa and human neuroblastoma SH-SY5Y cell lines." (PMID 29950972, 2018).
non-small cell lung carcinoma (3 papers, 2015 to 2024). A group of at least three distinct histological types of lung cancer, including non-small cell squamous cell carcinoma, adenocarcinoma, and large cell carcinoma. "It is worth noting that these observations align with the existing literature that has reported the overexpression of UBB and UBC in various cancer types, including PC and non-small-cell lung cancer." (PMID 38473264, 2024).
Parkinson disease (3 papers, 2011 to 2025). A progressive degenerative disorder of the central nervous system characterized by loss of dopamine producing neurons in the substantia nigra and the presence of Lewy bodies in the substantia nigra and locus coeruleus. "UBB transcription was previously shown to be upregulated in neurons of Parkinson’s disease patients." (PMID 40894048, 2025). "The PPI analysis showed that UBB genes play important roles in the Parkinson’s disease pathway." (PMID 29101267, 2018). "A case study using Parkinson disease (PD) has identified four candidate genes (UBB, SEPT5, GPR37 and TH) that ranked higher than our adaptive threshold, all of which are involved in the PD pathway." (PMID 21731658, 2011). "The four candidate genes are ubiquitin B (UBB), septin 5 (SEPT5), G protein-coupled receptor 37 (GPR37) and Tyrosine hydroxylase (TH), all of which have been involved in the Parkinson disease pathway." (PMID 21731658, 2011).
prostate carcinoma (3 papers, 2020 to 2025). A carcinoma that arises from epithelial cells of the prostate gland. "Lastly, unique hub-genes of naive CD4+ T-cells, such as HSPA8, are reported to be expressed in CD8+ T-cells in prostate cancer, while UBC, UBB, CTNNB1, and H3-3B are not reported, rendering them novel markers for naive CD4+ T-cells." (PMID 40906153, 2025).
clear cell renal cell carcinoma (2 papers, 2024). "To investigate the potential role of UBB in renal clear cell carcinoma, we conducted in vitro experiments." (PMID 38994370, 2024). "The results based on transcriptome data analysis and in vitro experiments demonstrated that UBB, a mitochondrial autophagy-related gene, has a very important role in renal clear cell carcinoma, which provides a new direction for potential clinical treatment." (PMID 38994370, 2024). "Taken together, these results suggest that the upregulation of UBB promotes the proliferation, invasion, and migration of renal clear cell carcinoma cells." (PMID 38994370, 2024).
dementia (2 papers, 2022 to 2023). Loss of intellectual abilities interfering with an individual's social and occupational functions. "Among the Parkinson’s genes, UBB was the main contributor to this loss in edges, dropping from an average of 10 edges in donors with no dementia to an average of 3 edges in donors with dementia." (PMID 36803416, 2023). "Not only the APP gene is responsible for dementia in DS, GATD3A, SOD1, ERG, BACE2, DSCR1/RCAN1, APOE (19q13.32), BACE1 (11q23.3), IL1B (2q14.1), GSAP (7q11.23), UBB (17p11.2), and IRS1 (2q36.3) genes may also play a major role in dementia in DS." (PMID 35676933, 2022).
gastric adenocarcinoma (2 papers, 2020 to 2024). "The knockdown of UBB triggers cell apoptosis and β-catenin decreasing, which could serve as pro-survival gene in gastric adenocarcinoma." (PMID 38346070, 2024). "Further in vitro experiments (i.e., using other GC cell lines such as AGS and SNU-16) and in vivo studies are needed to warrant UBB and UBC as potential therapeutic targets and Ub protein levels as a new biomarker in gastric adenocarcinoma." (PMID 32751694, 2020). "Our results identify UBB and UBC as pro-survival genes in primary gastric adenocarcinoma 23132/87 cells." (PMID 32751694, 2020). "Our preliminary evidence shows that combined targeting of poly-Ub genes UBB and UBC significantly affects the cellular Ub protein content in the two GC cell lines, being more detrimental for the viability of primary gastric adenocarcinoma 23132/87 cells." (PMID 32751694, 2020).